PPARG (peroxisome proliferator activated receptor gamma)
Diseases named in the same sentence as PPARG in open-access papers (continued):
Sharing a sentence is not in itself a finding about the gene and the disease.
cancer (continued). "Chronic pharmacological activation of PPARγ can in some cases also cause cancer in rats and mice." (PMID 19197366, 2008). "They found that β-carotenesignificantly increased PPARγ mRNA and protein levels ina time-dependent fashion, while 2-chloro-5-nitro-N-phenylbenzamide (GW9662), anirreversible PPARγ antagonist, attenuated apoptosis caused by β-carotene in cancer-transformed cells." (PMID 18779870, 2008). "In contrast,long-term continuous treatment with LA induces quiescent and dormancy in cancercells with PPARγ downregulation.These conditions might be associated with phenotypes of cancer stemcells/progenitor cells." (PMID 18551182, 2008). "Interactionswith PGC1-α are reduced in several cancers;and oppositely the known CoRs associated with PPARγ are overexpressed and thetranscriptional actions of PPARγ are repressed by epigenetic mechanismsinvolving HDAC3.Equally, the control of posttranslational modifications appears to be altered." (PMID 18528521, 2008). "Therefore,rosiglitazone and its analogues act through PPARγ to cause substantial andpersistent suppression of CXCR4 on cancer cells." (PMID 18779872, 2008). "Patients with ER-positive tumors might benefit from TZD exposuremore than those with ER-negative tumors, as the level of PPARγ expression issignificantly associated with the ER status of carcinoma cells." (PMID 18645617, 2008). "In Case 3, a CDK12 variant was detected in all cells of Regions A and B; whereas, four variants in ATRX, BRCA2, PIK3CA, and PPARG were detected specifically in Region A. All four variants displayed low VAFs (0.05–0.07), indicating a late molecular event present in a small subset of cancer cells." (PMID 39766052, 2024). "Similarly, we observed that all tested CRC cells converted adipocytes into cancer-associated adipocytes, which decreased lipid content and the expression of genes that are characteristic of adipocytes (including PPARγ, resistin, adiponectin, FABP4, perilipin, and LIPE)." (PMID 37316878, 2023). "Moreover, we found identical results in PPARγ or α deficient cell lines, demonstrating that the in vitro anti-cancer effects of GW6471 at these concentrations are likely off-target, although we cannot fully exclude differential GW6471 effects between tissues in vivo and the HAP1 cell line in vitro." (PMID 34984327, 2022). "Similarly, endogenous, weak PPARγ agonists such as fatty acids and eicosanoids have long been associated with an increased incidence of cancer, and their effect may be circumvented by COX2 inhibitors." (PMID 36074574, 2022). "PPARG encodes PPARγ, an inducible transcription factor that is considered a master regulator in lipid metabolism, with roles in fat, carbohydrate, and general energy metabolism, as well as insulin sensitivity, cell proliferation and differentiation, inflammation, and cancer." (PMID 34283828, 2021). "Notably, PPARγ functions have been linked to several pathologies, ranging from metabolic disorders to cardiovascular disease, chronic inflammation, neurodegenerative disorders, and cancer." (PMID 28208577, 2017). "Considering the fact that a common SNP may make a small-to-moderate contribution to the risk of cancer, this pooled-analysis urges the necessity of adequate sample sizes to get a precise measurement between PPARG c.1347C>T polymorphism and the development of cancer." (PMID 29254243, 2017). "Accordingly, the context-dependent REST activity modulated by E3 skipping may underlie the context-dependent effect of PPARγ on tumorigenesis, such that E3 skipping represents a potential therapeutic target that might be utilized for personalized medicine for cancer." (PMID 23614038, 2013). "PPARγ may be involved in the regulation of gene expression associated with inflammation and cancer." (PMID 22936949, 2012).
cancer (continued). "Peroxisome proliferator-activated receptor-γ (PPARγ) is a member of the nuclear receptor superfamily of ligand-activated transcription factors that plays an important role in the control of gene expression linked to a variety of physiological processes, including cancer." (PMID 22934105, 2012). "However, the chronic administration of PPAR agonists in human for the treatment of metabolic diseases may importantly increase the risk of developing cardiovascular diseases (e.g., for PPARγ agonists) and specific cancers (e.g., for PPARα agonists)." (PMID 23024649, 2012). "Hence, taking into consideration the diversity of human cancer, the expression of PPARγ may likely be dependent on tissue specificity and/or mutational events that are prerequisite for cancer development." (PMID 16854216, 2006). "The previous report showed that HT-29 cells expressed relatively high levels of PPARγ protein among cancer cells." (PMID 41019996, 2025). "The outcome of PPARγ modulation depends on cancer type, disease stage, tissue specificity, and the surrounding inflammatory and metabolic environment." (PMID 41476922, 2025). "In conclusion, I2 showed anti-cancer (cytotoxic, anti-invasive) and pro-cancer (pro-neurite, lipid accumulation, desmoplasia) effects through a PPARG-independent mechanism." (PMID 40869121, 2025). "Ultimately, advancing the field will require a multidisciplinary effort spanning molecular biology, pharmacology, oncology, and clinical nutrition to fully harness the therapeutic potential of PPARγ in cancer cachexia." (PMID 41476922, 2025). "Beyond their PPARγ‐dependent effects, TZDs exhibit anti‐cancer properties through various PPARγ‐independent pathways." (PMID 40387523, 2025). "In non-cancer models of muscle atrophy, such as diabetes-induced sarcopenia and angiotensin II-induced wasting, PPARγ expression is suppressed, whereas its pharmacological activation alleviates muscle loss and promotes regeneration following injury." (PMID 41476922, 2025). "PGC1α can govern carcinogenesis, progression, and metabolic status in various cancers, such as renal clear cell, prostate, endometrial, breast cancers, and melanoma, through cooperation with approximately twenty nuclear factors (PPARγ, HNF4, NRF1/2, and ERR)." (PMID 40603870, 2025). "Specifically, FABP4, regulated by PPARγ signaling, is upregulated in cancer cells, leading to reduced intracellular lipid droplets and suppressed cell proliferation, thereby promoting lipolysis." (PMID 41369331, 2025). "Acting as a PPARG antagonist, betulinic acid has been reported to induce apoptosis in various cancer cell types through the activation of ROS production." (PMID 40564064, 2025). "Conversely, in cancer cachexia, pathological browning arises in a pro-inflammatory, catabolic milieu where PPARγ signaling is suppressed." (PMID 41476922, 2025). "Activation of PPARG by molecules secreted by astrocytes supports cancer cell viability, with PPARG regulation tightly controlled by epigenetic mechanisms." (PMID 40016470, 2025). "Pioglitazone, a peroxisome proliferator-activated receptor gamma (PPARγ) agonist, exhibits anti-proliferative and pro-differentiation effects in several cancer models." (PMID 41050082, 2025). "Activation of PPARγ exerts anti-proliferative, pro-apoptotic, and anti-inflammatory effects by inhibiting cancer-promoting pathways such as the Wnt/β-catenin and modulating estrogen receptor (ER) signaling." (PMID 40926269, 2025). "PPARG ligands can either suppress or enhance AR signaling depending on the cancer’s response to castration, whereas AR activation reduces PPARG levels." (PMID 40458476, 2025).
cancer (continued). "In contrast, several studies have reported on the dynamic regulation of PPARγ in suppressing the proliferation of cancer cells." (PMID 40161411, 2025). "Previous studies have reported that PPARG pathway promotes ferroptosis resistance in various cancers." (PMID 40694956, 2025). "Our study thus outlined increasing peroxisomes, most importantly via the use of PPARγ agonists, as a therapeutic strategy against cancer development and invasiveness." (PMID 41373547, 2025). "Here PPARγ functions as a protective ally in cancer cachexia by preserving skeletal muscle mass and mitigating inflammation through suppression of pro-inflammatory signaling cascades and modulation of immune cell dynamics." (PMID 41476922, 2025). "Despite substantial progress, the role of PPARγ in cancer cachexia remains incompletely defined due to its tissue-specific and context-dependent actions." (PMID 41476922, 2025). "PPARγ significantly influences cancer cell proliferation, invasion, and metastasis via alterations in EMT markers." (PMID 40361374, 2025). "PPARγ‐dependent mechanisms of TZDs contribute to cancer suppression by inducing cell cycle arrest, apoptosis, and inhibiting angiogenesis." (PMID 40387523, 2025). "Specifically, the downregulation of key lipid metabolism regulators SREBP1 and PPARγ following Piper Longum treatment suggests disruption of lipogenic programs that sustain cancer cell proliferation." (PMID 40855327, 2025). "PPARγ, a nuclear receptor, is known to reduce inflammation and oxidative stress, promote cell cycle arrest, and induce apoptosis, offering new avenues for cancer treatment." (PMID 40286213, 2025). "In short, the current evidence positions PPARγ as a systemic and multifaceted regulator with therapeutic potential for combating muscle wasting in cancer cachexia." (PMID 41476922, 2025). "Owing to its multifaceted regulatory functions, PPARγ has garnered significant interest in cancer cachexia." (PMID 41476922, 2025). "Research into Wnt/β-catenin signaling reveals opposing roles for peroxisome proliferator-activated receptor-gamma (PPARγ), which is downregulated in chronic inflammation and cancer." (PMID 40732979, 2025). "Antiandrogens stimulate peroxisome proliferator-activated receptor gamma (PPARG) signaling and cancer progression." (PMID 40869121, 2025). "Promising evidence that PPARγ agonists prevent the survival of colon CSCs offers a new strategy for controlling cancer progression." (PMID 39875357, 2025). "Due to its influence on these processes, PPARG is being investigated as a target for treating diseases like type 2 diabetes and even cancer." (PMID 40500799, 2025). "Taken together, PPARγ emerges as a multifaceted regulator of adipose tissue homeostasis in cancer cachexia, integrating lipid metabolism, inflammatory signaling, and thermogenic control." (PMID 41476922, 2025). "These safety issues highlight the limitations of full PPARγ activation in cachectic cancer patients." (PMID 41476922, 2025). "In adipose tissue, PPARγ is a master regulator of lipid storage and adipogenesis, yet cancer cachexia is characterized by enhanced lipolysis, impaired lipogenesis, and white adipose tissue catabolism, leading to systemic energy imbalance." (PMID 41476922, 2025). "Alpinetin, a naturally occurring flavonoid, has emerged as a promising PPARγ-dependent modulator of cancer cachexia." (PMID 41476922, 2025). "In summary, this study was the first to comprehensively analyze the expression patterns of PPARA, PPARD and PPARG in multiple cancers including in STAD." (PMID 38529307, 2024). "Cancer cells usually show decreased expression of PPARγ and increased expression of canonical Wnt/β-catenin." (PMID 39272080, 2024). "We observed that PPARA and PPARG genes were upregulated in most para-cancer samples, while PPARD was upregulated in cancer tissues." (PMID 38529307, 2024).
cancer (continued). "Recent studies have shown that PPARγ regulators regulate immune responses, cancer cell proliferation, lipid metabolism, and angiogenesis." (PMID 39765861, 2024). "In experimental studies, curcumin and synthetic analogs of curcumin were demonstrated to induce PPARγ expression in glial and carcinoma cells, thereby providing neuroprotective and anti-cancer effects." (PMID 38473849, 2024). "Intriguingly, enhanced anti-cancer activities were observed upon the administration of a PPARγ antagonist in conjunction with an inhibitor targeting sonic hedgehog signaling intermediate molecule, smoothened." (PMID 39327610, 2024). "Some studies suggested that SND1 plays important roles in cancer by interacting with other transcription factors, including PPARγ, signal transducer and activator of transcription 5/6 (STAT6/5) and myeloblastosis oncogene (c-Myb)." (PMID 39436790, 2024). "Pathway analysis also showed that PPARG significantly impacts chemosensitivity by regulating key cellular processes and signaling pathways involved in cancer cell response to chemotherapy." (PMID 38505269, 2024). "Recently, studies have reported the anticancer properties of rosiglitazone related to its ability to bind peroxisome proliferator receptor γ (PPARγ), which has various effects on cancer and can inhibit cell proliferation." (PMID 38920636, 2024). "Previous studies have shown that hsa-miR-4465 plays a key role in regulating glucose metabolism, glutamine metabolism, autophagy and cancer progression in various cell types, while miR-27-3p inhibits adipogenesis by inhibiting PPARγ." (PMID 39844908, 2024). "Pparγ and Scd1 mRNA expression levels, which were prohibited by cancer cachexia, were recovered by DOE administration." (PMID 39519503, 2024). "As HNF4A acts as a selective agonist of the peroxisome proliferator-activated receptor gamma (PPARγ), our analyses suggest its potential as a novel biomarker and target for cancer prevention." (PMID 38645221, 2024). "PPARγ agonists, such as rosiglitazone, have been extensively studied in the induction of differentiation in malignant tumors and induce cell transdifferentiation in various malignancies." (PMID 37935080, 2024). "Both Rosiglitazone and Pioglitazone effectively induced adipogenesis in cancer cells, marked by PPARγ and C/EBPα upregulation, cytoskeleton rearrangement, and lipid droplet accumulation." (PMID 39273076, 2024). "Our findings uncovered the potential of the peroxisome proliferator-activated receptor-γ (PPARG) regulon for predicting ICI outcomes across multiple cancer types." (PMID 38773508, 2024). "In vitro studies have demonstrated that PPARγ agonists, including TZDs, possess several anti-cancer properties, such as inducing apoptosis and inhibiting growth." (PMID 38254789, 2024). "Other widely studied NRs, PPARα, PPARβ/δ and PPARγ, play important roles in both cancer progression and inhibition via modulation of metabolism, inflammation, cell proliferation and apoptosis in various cancer types in a context-dependent manner." (PMID 39199690, 2024). "The expression profiles of three PPAR genes (PPARA, PPARD and PPARG) were downloaded from The Cancer Genome Atlas (TCGA) dataset to analyze their expression patterns across pan-cancer." (PMID 38529307, 2024). "The nuclear receptor PPARγ, a transcriptional master regulator of cell metabolism, inhibits the growth of several common cancers including CC." (PMID 36875279, 2023). "There was little evidence to support associations between genetically proxied PPARG perturbation and colorectal or overall cancer risk or between genetically proxied ABCC8 or GLP1R perturbation with risk across cancer endpoints." (PMID 37171501, 2023). "Collectively, these findings indicate the presence of PPARG genetic alterations and differential expression in cancer tissues, particularly in LIHC and PAAD." (PMID 38044948, 2023).
cancer (continued). "In particular, the receptor is involved in the occurrence and progression of cancer, and agonist ligands that modulate the activity of PPARγ have been regarded as potential drugs for chemoprevention and the treatment of cancer." (PMID 37649895, 2023). "Through our investigation, we confirmed the variability of PPARG expression in various types of cancers by analyzing PPARG gene expression levels in human cancers using the TCGA database." (PMID 38044948, 2023). "Nevertheless, the promotion of PPARγ-dependent SIRT1 expression in HeLa cancer cells would certainly lead to higher cancer cell viability." (PMID 37762053, 2023). "It is expected that probiotic GS4, which have biohydrogenation ability to produce CLA, would enable them to modulate cancer cell metabolism through the modulation of PPARγ in terms of their antiproliferative efficiency." (PMID 36875279, 2023). "The development of most cancers is often accompanied by downregulation of PPARγ and upregulation of Wnt/β-catenin pathway." (PMID 37251321, 2023). "In this study, we observed heterogeneous PPARG mRNA expression levels across various types of cancer." (PMID 38044948, 2023). "Both intracellular and extracellular fatty acids are present in high amounts and are then delivered to the nucleus of cancer cells by E-FABP as a signaling molecule to activate PPARγ." (PMID 38136624, 2023). "Our findings highlight the variability of PPARG expression across different types of cancer and its impact on patient survival and prognosis." (PMID 38044948, 2023). "PPARγ overexpression occurs in various types of cancer, so rosiglitazone is one of the potential anti-cancer candidates." (PMID 37446385, 2023). "PPARγ is active during cancer, and it has been suggested that PPARγ activates autophagy in a self-sufficient manner." (PMID 37190124, 2023). "The TCGA dataset analysis reveals a significant correlation between PPARG expression and the occurrence of cancer, as well as a poor prognosis." (PMID 38044948, 2023). "We examined the expression features of PPARG in cancer, including its effects on genomic stability, the immune microenvironment, and potential molecular mechanisms." (PMID 38044948, 2023). "Note the role of PPARγ-induced apoptosis in cancer cells has been the subject of reviews, and depicted in Fig. 8C1–C2 are the results of WB experiments." (PMID 37208732, 2023). "Even though the beneficial effect of PPARγ in cancer has been confirmed in several studies, the recent one brings a new perspective to the matter." (PMID 36834531, 2023). "In terms of metabolism, ETV4 activates PPARγ signaling, which directly regulated glycolysis and fatty acid metabolism in cancer cells." (PMID 37692839, 2023). "Taken together, the present findings provide a rationale for further preclinical/clinical studies to develop new therapeutic approaches for the prevention and/or treatment of keratinocyte-derived cancer through the activation of PPARγ." (PMID 37048080, 2023). "This approach enabled us to analyze the differences in PPARG mRNA expression across 27 types of cancer." (PMID 38044948, 2023). "Although the majority of in vitro studies confirmed the beneficiary role of PPARγ agonists in cancer chemoprevention and suggested their antiproliferative and anti-metastatic properties, the results of clinical studies are not so optimistic." (PMID 36834531, 2023). "PPARγ can inhibit the growth of malignant tumors by affecting cell proliferation, apoptosis, angiogenesis, inflammation, and metastasis." (PMID 37170184, 2023). "It was shown that troglitazone (a PPARγ agonist) induces autophagy in these cancer cells as shown by an increase in lysosomal acidification." (PMID 37190124, 2023). "In cancer cells, PPARγ promotes the adaptive regulation of lipid metabolism in response to microenvironment changes, and its modulation by small molecules broadly suppresses EMT progression." (PMID 37048080, 2023).